PTX3 (pentraxin 3)
Diseases named in the same sentence as PTX3 in open-access papers (continued):
Sharing a sentence is not in itself a finding about the gene and the disease.
endothelial dysfunction (continued). "The role of PTX3 in endothelial dysfunction is debated, where earlier studies have suggested PTX3 to have a detrimental role, whereas recent studies have also shown that PTX3 has an atheroprotective role by inhibiting leukocyte adherence to the endothelium." (PMID 24060373, 2013). "Interestingly, vasculitis in autoimmune disease is influencing PTX3 levels, and PTX3 is involved in vascular inflammation and endothelial dysfunction." (PMID 39919333, 2025). "For this reason, PTX‐3 is mainly studied as an indicator of endothelial dysfunction." (PMID 41496770, 2025). "PTX‐3 is also being investigated as a marker of endothelial dysfunction in MH." (PMID 41496770, 2025). "In metabolic disorders, PTX-3 has been reported to exert beneficial effects by influencing adipose tissue homeostasis, modulating macrophage polarization towards an anti-inflammatory (M2) phenotype, and reducing endothelial dysfunction." (PMID 40299501, 2025). "Elevated PTX3 levels are associated with higher CKD patient mortality,increased CKD and CVD risk.Endothelial dysfunction, often linked to heightenedPTX 3 levels, is hypothesized to contribute to the augmentedCVD risk in CKD." (PMID 39139165, 2024). "Also, pentraxin-3 (PTX3), an acute-phase protein, is related to vascular inflammation and endothelial dysfunction by modulating inflammatory cells and decreasing nitric oxide (NO) synthesis within endothelial cells." (PMID 39062191, 2024). "However, the role of PTX‐3 in the development of endothelial dysfunction and vascular remodeling remains controversial." (PMID 39414396, 2024). "Secondly, the researchers did not measure the natural coagulation system proteins or even endothelial dysfunction biomarkers, so the specific coagulation disturbances associated with PTX3 and SARS-CoV-2 in this cohort of patients were not assessed." (PMID 37408184, 2023). "PTX3 modulates endothelial dysfunction by its direct effect on endothelial cells." (PMID 35563387, 2022). "Measures of increased risk for future CVD events and endothelial dysfunction, including flow-mediated dilatation (FMD), pentraxin-3 (PTX3), and carotid intima-media thickness (cIMT), and fibroblast growth factor 23 (FGF23) as a marker of atherosclerotic vascular disease were compared between groups." (PMID 35629299, 2022). "PTX3 may also be an active mediator of endothelial dysfunction and atherosclerotic plaque vulnerability." (PMID 33210471, 2021). "Taken together, these data could suggest that endothelial dysfunction and EndMT process, observed in I/R animals, firstly occurred in EC expressing PTX3." (PMID 33875620, 2021). "Therefore, PTX3 levels are believed to be a true independent indicator of local inflammation and are thought to reflect endothelial dysfunction more accurately than CPR." (PMID 32244987, 2020). "PTX3 is related with local endothelial dysfunction, but its exact role in migraine is still unknown." (PMID 32731573, 2020). "Diagnosis of CM was 68.4 times more likely in an individual with levels of PTX3 ≥ 832.5 pg/mL, suggesting that PTX3 could be a novel biomarker of endothelial dysfunction in CM." (PMID 32244987, 2020). "Furthermore, PTX-3 interacts with P-selectin, promoting lymphocyte recruitment, vascular inflammation, and endothelial dysfunction that can result in morphological alterations." (PMID 32670996, 2020). "Furthermore, PTX levels ≥ 832.5 pg/mL predicted diagnosis of CM, thus indicating the potential role of PTX3 as a potential biomarker of endothelial dysfunction in CM." (PMID 32244987, 2020). "In vivo administration of PTX3 induced endothelial dysfunction and increased blood pressure." (PMID 31354697, 2019). "Other studies have reported that PTX3 levels are higher in women with preeclampsia, speculating on its contribution to endothelial dysfunction." (PMID 30733816, 2019).
endothelial dysfunction (continued). "More studies are needed to better characterize direct correlation between the ultrastructural and bioenergetic changes induced by PTX3 with endothelial dysfunction, and to better understand the mechanisms involved in age-related cerebro- and cardio-vascular diseases." (PMID 30733816, 2019). "Furthermore, levels of PTX3 correlate with other indicators of endothelial dysfunction such as the soluble VCAM-1 and vWf." (PMID 29435447, 2017). "Additionally, indicators of endothelial dysfunction, including soluble vascular cell adhesion molecule-1 (sVCAM-1) and pentraxin-3 (PTX3), may help differentiate NBD from other neuroinflammatory conditions and monitor therapeutic efficacy." (PMID 40254498, 2025). "However, results from clinical studies have so far provided contrasting results, with these findings indicating a debatable role of PTX3 as related to active mediation of endothelial dysfunction, atherosclerotic plaque vulnerability, and worsened outcomes after ischemic events." (PMID 33210471, 2021). "Our results suggest that PTX3 could be a potential biomarker of endothelial dysfunction in CM." (PMID 32244987, 2020). "Moreover, inhibition of MMP1 protected mesenteric arteries against the endothelial dysfunction promoted by PTX3, an effect absent in P-selectin-deficient mice." (PMID 31354697, 2019). "However, whether the increased levels of PTX-3 observed in patients with OSA + HTN are an epiphenomenon of the atherosclerotic process or whether the protein has an active role in development of endothelial dysfunction is beyond the scope of the present study." (PMID 26697221, 2015). "As previous data imply that PTX3 is involved in vascular pathology and that adipose tissue mass may influence circulating PTX3 levels, we aimed to study the importance of adipose tissue expression of PTX3 in the uremic milieu and its relation to endothelial dysfunction parameters." (PMID 23658833, 2013). "PTX-3 has been increasingly studied as a biomarker of CVD, including myocardial injury, due to its role in inflammation, endothelial dysfunction and tissue damage." (PMID 39941683, 2025). "Pentraxin-3 (PTX3) has emerged as a key biomarker of inflammation and endothelial dysfunction in DM." (PMID 40299501, 2025). "The aim of this study, therefore, was to investigate the relationship between levels of PTX3 and sTWEAK and FMD in order to elucidate their potential role as markers of endothelial dysfunction in CM patients during interictal periods." (PMID 32244987, 2020). "Our aim was to evaluate the role of pentraxin 3 (PTX3) and soluble tumour necrosis factor-like weak inducer of apoptosis (sTWEAK) as potential biomarkers of endothelial dysfunction in chronic migraine (CM)." (PMID 32244987, 2020). "Therefore, PTX3 may be a bridge between inflammation and endothelial dysfunction." (PMID 31780874, 2019). "In DKD patients, elevated circulating Pentraxin 3 (PTX3), an acute-phase reactant that reflects endothelial dysfunction, may be used as a biomarker in detecting early renal damage." (PMID 37092467, 2023). "CaD may inhibit the expression of PTX3 by altering the IKK/IKB/NF-κB pathway, thereby improving endothelial dysfunction on the cellular level." (PMID 31780874, 2019). "Our results suggested that CaD may inhibit the expression of PTX3 by altering the IKK/IKB/NF-κB pathway, thereby improving endothelial dysfunction in HUVECs." (PMID 31780874, 2019). "With regard to markers of endothelial dysfunction/activation, plasma levels of vWf, sVCAM-1, MCP-1, and PTX3 were significantly increased in RA patients, whereas differences in the concentrations of sE-selectin were weakened after the standardization of the results to gender and age." (PMID 24864133, 2014). "Pentraxin-3 (PTX3) is a plasma protein involving in chronic inflammation and Interleukin-6 (IL-6) as one of the most common molecules contributes to inflammation may promote endothelial dysfunction and the progression of vascular complication." (PMID 35883173, 2022).
endothelial dysfunction (continued). "However, it has been reported that PTX3 may primarily reflect endothelial dysfunction rather than systemic inflammation." (PMID 29941014, 2018). "However, the association observed between PTX-3 and CKD is independent of inflammatory and endothelial dysfunction biomarker C-reactive protein in our study, suggesting that PTX-3 might play a role in pathogenesis of CKD via an additional pathway such as abnormal angiogenesis." (PMID 29783932, 2018).
breast carcinoma (55 papers, 2012 to 2025). "PTX3 as a small extracellular vesicle-associated protein, is negatively associated with relapse-free survival and accelerates chemotherapy-induced breast cancer metastasis." (PMID 41479916, 2025). "Several studies have demonstrated that PTX3 expression is associated with progression in various types of cancers, such as head and neck cancer, breast cancer, gastric cancer, melanoma, hepatocellular carcinoma, and cervical cancer." (PMID 38243273, 2024). "In breast cancer, cancer-associated adipocytes have been shown to exhibit increased expression of PTX3, which plays a role in promoting more aggressive tumor behavior." (PMID 39594709, 2024). "Our recent work revealed that in breast cancer, a high level of PTX3 in CAFs was associated with a poor prognosis for survival and that PTX3 contributed to drug resistance, stemness, and metastasis." (PMID 38243273, 2024). "In breast cancer cells, PTX3 has been implicated in tumor cell migration through its regulation of protein kinase C ζ (PKCζ) activation." (PMID 39594709, 2024). "A study conducted by Choi and colleagues underlined the up-regulation of PTX-3 expression in 64 individuals diagnosed with breast cancer and also in distant bone metastases, which represent one of the most common metastases." (PMID 36499628, 2022). "Here, we further demonstrated that PTX3 is associated with high metastasis of primary breast cancers and poor prognosis." (PMID 35090088, 2022). "We assessed the involvement in TNBC of CEBPD and PTX3 expression in breast cancer‐associated fibroblasts (BCAFs)." (PMID 35090088, 2022). "The researchers underlined the potential activity of PTX-3 as a prognostic biomarker in breast cancer." (PMID 36499628, 2022). "Noteworthy, we also found that the presence of PTX3-positive BOLCs significantly increases the risk of developing breast cancer metastasis to bone within 5 years from first histological diagnosis." (PMID 33584725, 2020). "Nevertheless, the secretion of PTX3 in breast cancer was elevated and linked to stem-like structures, epithelial-mesenchymal transition, migration, invasion, and metastasis." (PMID 33178316, 2020). "Higher PTX3 protein expression was also associated with disease recurrence in the CPTAC breast cancer cohort." (PMID 32427938, 2020). "The activation of PTX3 plays a critical role in tumor-associated inflammation and chemoresistance during breast cancer treatment." (PMID 30740360, 2019). "In this study, we demonstrated that PTX3 expression is associated with stemness and epithelial-mesenchymal transition in breast cancer cells." (PMID 30740360, 2019). "Expression of PTX3 in breast cancer is high and is associated with stem-like features, epithelial-mesenchymal transition, migration, invasion, and metastasis." (PMID 30740360, 2019). "Our findings provide evidence for the key role of PTX3 and its related mechanism in bone metastasis of breast cancer, possibly reflecting the osteolytic process of breast cancer associated with inflammation." (PMID 24457902, 2014). "To investigate the association of the PTX3 gene expression signature with bone metastasis, we analyzed a cohort of 64 breast cancer patients for whom genome-wide gene expression data was available." (PMID 24457902, 2014). "Gene expression data from primary breast cancer patients also displayed associations between PTX3 signature and survival time in a cohort of 203 primary breast cancer tissues of human breast cancer patients." (PMID 24457902, 2014). "Notably, PTX3 upregulation is closely linked to breast cancer stem cell-like traits, which confer self-renewal and differentiation capacities, contributing to tumor progression, recurrence, and drug resistance." (PMID 41479916, 2025). "Researchers remind that the importance of novel drug development in breast cancer and pipelines could be based on inhibitors of PTX-3/CD44 interaction or PTX-3 use in association with mesenchymal markers as the target." (PMID 36499628, 2022).
breast carcinoma (continued). "PTX-3 has been suggested to play a significant role in tumour-associated inflammation and was shown to be up-regulated in several malignancies, including melanoma, prostate cancer, breast cancer, and lung cancer." (PMID 33776564, 2021). "To determine whether PTX3 expression in breast cancer cells is associated with stem-like properties and epithelial-mesenchymal transition, we either down-regulated PTX3 expression in MCF-7 and MDA-MB-231 cells using siPTX3 or treated the cells with rhPTX3." (PMID 30740360, 2019). "Upregulation of PTX3 gene expression was observed associated to a stromal signature in ovarian cancer, and has been described in aggressive breast cancer and distant bone metastases, anaplastic thyroid carcinoma, soft tissue liposarcoma, prostate cancer, and glioblastoma." (PMID 31019517, 2019). "We examined the effect of PTX3 deficiency on the proliferation of breast cancer cells." (PMID 24457902, 2014). "The cancer stemness-promoting PTX3 is induced by PI3K activation in basal-like breast cancer cells through AKT- and NF-κB-dependent signaling." (PMID 41479916, 2025). "Future research should focus on evaluating the prognostic value of PTX3 in breast cancer and developing targeted therapies aimed at this molecule." (PMID 41479916, 2025). "PTX3 is upregulated in aggressive breast cancer cell lines by bioinformatic analyses of public database." (PMID 41479916, 2025). "The overexpression of PTX3 in mammary carcinoma cells inhibits FGF2-dependent stimulation of capillary morphogenesis." (PMID 41479916, 2025). "Bevacizumab, an anti-vascular endothelial growth factor antibody used in breast cancer treatment, was found to elevate peripheral PTX3 levels in patients." (PMID 41479916, 2025). "Peripheral PTX3 levels are increased in breast cancer patients receiving bevacizumab, compared to those receiving chemotherapy." (PMID 41479916, 2025). "Conversely, doxorubicin-induced PTX3 has been shown to positively regulate breast cancer metastasis." (PMID 41479916, 2025). "PTX3 is upregulated in bone metastases of breast cancer, correlated with poor survival while inducing cell migration, macrophage chemotaxis and osteoclast differentiation." (PMID 41479916, 2025). "PTX3 is strongly expressed in bone metastases of breast cancer, closely related to the transformation of epithelial cells with mesenchymal characteristics into breast osteoblast-like cells." (PMID 41479916, 2025). "Their study further demonstrated that POLCs serve as a negative prognostic marker for prostate cancer bone metastasis, with PTX3 playing a significant role in the metastatic process, analogous to its involvement in breast cancer bone metastasis." (PMID 41479916, 2025). "Collectively, in breast cancer, PTX3 overexpression can promote stem-like properties through various signaling pathways, including NF-κB, Wnt/β-catenin, AKT, and JNK." (PMID 41479916, 2025). "Our previous study showed that disruption of the PTX3/CD44 interaction attenuates breast cancer progression." (PMID 38243273, 2024). "The previous study also revealed that PTX3 promotes breast cancer cell proliferation and metastasis." (PMID 39187920, 2024). "The expression of PTX3 has been analyzed in tumor samples from BC patients using the Gene Expression-Based Outcome for Breast Cancer Online (GOBO)." (PMID 37749607, 2023). "The expression of PTX3 in BC tumor samples and in BC cell lines has been analyzed using the Gene Expression-Based Outcome for Breast Cancer Online (GOBO), qPCR, Western blot and ELISA assay." (PMID 37749607, 2023). "Further, the inflammatory cytokine pentraxin 3 (PTX3) has been observed to change in poorly‐differentiated clinical breast cancer samples and the S100 calcium binding family member S100A4 has been implicated in endometrial cancer progression through EMT." (PMID 37217832, 2023).